MMP9 (matrix metallopeptidase 9)
Diseases named in the same sentence as MMP9 in open-access papers (continued):
Sharing a sentence is not in itself a finding about the gene and the disease.
tumor (continued). "Tumor buds overexpress protein markers associated with tumor cell migration and invasion such as matrix metallopeptidase 2 (MMP2), MMP9 and cathepsinB (CTSB)." (PMID 25884643, 2015). "There are many cytokines secreted by aHSCs that are associated with tumor invasion and metastasis, including HGF, EGF, IL-1, IL-2, IL-6, MMP-2, MMP-9, TGF-β, TNF-α, VEGF and members of the Wnt signaling family." (PMID 26517671, 2015). "AXL in particular has been implicated in metastasis in multiple tumor types and facilitates EMT in addition to upregulation of MMP9." (PMID 26328272, 2015). "CHI3L1-positive tumor cells armed with MMP9 and VEGF seem capable to pass the neighboring matrix and enter the bloodstream, possibly via newly formed microvessels." (PMID 26425658, 2015). "The immune-reactivity scores for the expression of mTOR and p-mTOR as well as for MMP2, MMP7, and MMP9 in the tumor center correlated each with its expression at the invasive front (p < 0.001)." (PMID 26652716, 2015). "MMP-9 was found to promote tumor proliferation in a human papilloma virus- (HPV-) 16 skin carcinogenesis model." (PMID 26819959, 2015). "More specifically, we found that expression of MMP-9 in stromal was repressed by the activation of the EGR1 gene induced by EGF secreted by tumor cells and it correlates with decreased MMP-9." (PMID 25897433, 2015). "Using gelatin zymography assays, we found that MMP-9/NGAL activity was significantly increased in tumor tissues (TT) and preoperative urine samples (Preop-1d urine)." (PMID 26663949, 2015). "When RECK is down-regulated, the activity of MMP-9, a key enzyme involved in tumor invasion and metastasis, is increased." (PMID 25885317, 2015). "We also detected the MMP-9 and TN-C can be expressed in the same tumor region through serial section, and identified as co-expression." (PMID 26652622, 2015). "The patients of tumor MMP-9 expression had more advanced stage (p = 0.001), therefore, they received more postoperative treatment (p = 0.000)." (PMID 25888323, 2015). "Curcumin also reduces the MMP-2 and MMP-9 expression, along with the suppression of growth and invasion potential of tumor cells in culture and xenograft experiments." (PMID 25600295, 2015). "Leptin treatment also showed increase in MMP-9 expression in hepatic cancer cells and endothelial cells to induce invasion of tumor cells." (PMID 25704884, 2015). "MMP2 and MMP9 play vital roles in tumor metastasis and invasion via the degradation of various proteins of the extracellular matrix and destruction of histological barriers." (PMID 26649302, 2015). "One well-known substrate for MMP3 is pro-MMP9, which has been reported to be a potent mediator of tumor progression." (PMID 26008967, 2015). "The results of the present study confirmed that the overexpression of MMP-2 and MMP-9 is likely to increase tumor invasion and metastasis." (PMID 25667651, 2015). "First, there were differences among previous studies in the definition of tumor MMP-9 positivity and the appropriate cut-off value." (PMID 25888323, 2015). "MMP-9 and TN-C is primarily overexpressed in the stroma but exists in part in the cytoplasm of tumor cells." (PMID 26652622, 2015). "In conclusion, these effects of dietary 2-DG on blood glucose, insulin, PI3K/Akt signaling, proliferation, immune status and MMP-9 activity provide a plausible mechanism for the tumor inhibitory effects of such metabolic intervention." (PMID 26135741, 2015). "Some transcription factors (such as SNAIL and SLUG) and matrix metalloproteinases (MMP2 and MMP9), were widely interpreted as the critical molecules in tumor invasion." (PMID 26575197, 2015). "Recently, exogenous gene transfer of MMP-9 was shown to suppress tumours by increasing neutrophil infiltration into the tumour site, a process that enhances macrophage secretion of pro-inflammatory cytokines and decreases IL-10 production." (PMID 25588705, 2015).
tumor (continued). "And these results suggest that the endogenous cleavage products of C3f at L1311–L1312 in serum are processed by tumor cell secreting MMP-9." (PMID 25788424, 2015). "In turn, MDSCs, through the upregulation of molecules such as VEGF, Bv8 and MMP9, can favor angiogenesis, tumor progression and tumor immune evasion." (PMID 25607954, 2015). "MMP-2 and MMP-9 are the key members of the MMP family, and they are closely associated with tumor metastasis since they can degrade the extracellular matrix and disrupt the basement membrane." (PMID 25452809, 2015). "TNFAIP3 inhibits the activity of NF-κB, which strongly facilitates the tumor progression through MMP9 expression, and represses cell division and inflammation." (PMID 26367773, 2015). "Simultaneously, the MMP-2 and MMP-9 protein expression of the tumor xenograft were downregulated in mice injected with SiCHD1L/MDA231 cells." (PMID 26599012, 2015). "MMPs, a family of zinc-containing proteolytic enzymes, facilitate tumor invasion and metastasis, and an enhanced expression of MMP-9 has been shown to be correlated with the progression and invasion of HCC." (PMID 26057631, 2015). "We further investigated the impact of tumor invasiveness on the prognosis of Cezanne expression in HCC by using MMP-9 marker as an indicator for invasive potential of tumor cells." (PMID 25638165, 2015). "MMPs secreted by stromal cells, especiallyMMP-2, MMP-3 and MMP-9, contribute equally or even more to tumor cell invasion than MMPs secreted from cancer cells." (PMID 25629807, 2015). "MMP-2 and MMP-9 selectively degrade type IV collagen and laminin, which constitutes the basement membrane, and contribute to tumor proliferation." (PMID 26690480, 2015). "MMP-9, which degrades basement membrane collagen, has been shown to promote tumor cell invasion and metastasis and decrease survival in many types of cancer." (PMID 25405331, 2015). "We found that the density of MMP9-expressing cells was significantly reduced by 51.9% in the tumours of phenytoin-treated animals (P < 0.01)." (PMID 25623198, 2015). "Matrix metalloproteinase 9 (MMP9, gelatinase B) production and secretion by tumour cells is a critical element involved in promoting metastasis." (PMID 25605249, 2015). "CD44-mediated localization of MMP-9 on tumor cells can regulate tumor cell motility, growth factor activation, and survival mechanisms." (PMID 25999946, 2015). "Degradation of extracellular matrix by matrix metalloproteinases (MMPs) was a first step for cancer cell migration and invasion, so MMP-9 plays an important role in tumor invasion." (PMID 26090427, 2015). "MMP9 is responsible for formation of leaky vasculature in the premetastatic lung and support of tumor cells survival in this organ." (PMID 26648665, 2015). "Similar results were obtained when the correlation of TSP50/p65 and TSP50/MMP9 expression with tumor grade was tested." (PMID 25811800, 2015). "In the context of radiation, the secretion of MMP9 by BMDCs leads to an induction in angiogenesis and tumor growth." (PMID 26348470, 2015). "In this study, we investigated the prognostic value of tumor MMP-9 expression and other clinicopathologic factors in patients with completely resected NSCLC." (PMID 25888323, 2015). "Our findings that local radiation enhances the recruitment of macrophages to the tumor as well as increases MMP9 expression in these cells suggest a role for macrophages in promoting metastasis following radiotherapy." (PMID 26348470, 2015). "These two compounds suppressed tumor growth both in vitro and in vivo by inhibiting NF-κB and metalloproteinase-9 (MMP-9) activity." (PMID 25918934, 2015). "We found that nicotine enhanced MMP-9 expression in the tumor tissue and both nicotine-induced and basal MMP-9 expression was decreased by BEL." (PMID 26588686, 2015).
tumor (continued). "In this study, we suggest a different approach by examining the expression of MMP-9 within the tumor microenvironment, as well as in the blood circulation of mice bearing HeyA8-MDR-induced tumors." (PMID 25788424, 2015). "Neutrophil-derived MMP9 has also been shown to contribute to tumor angiogenesis and progression of squamous cell carcinoma." (PMID 26648665, 2015). "Staining of mTOR in the tumor center correlated with p-mTOR (r = 0.195, p = 0.028), and there was a positive association MMP2 with MMP9 at the invasive front (r = 0.214, p = 0.015)." (PMID 26652716, 2015). "Where integrin linked kinase (ILK) has been implicated in carcinogenesis, ILK-intestinal epithelial cell knockout mice showed reduced tumour growth and MMP-9 expression in experimentally induced CAC." (PMID 25948887, 2015). "It should be noted that there are two previously published articles presenting data that CLU stimulates MMP9 expression in cell culture models: leukocytes and tumor cells." (PMID 26402857, 2015). "The importance of MMP2 and MMP9 in tumor progression, angiogenesis, and metastasis suggests that targeting them with imaging agents would be a useful strategy to noninvasively detect and characterize solid tumors." (PMID 26540114, 2015). "Other studies suggest that chemokine C-X-C motif receptor type 4 (CXCR4) binding to CAF-secreted chemokine C-X-C motif ligand 12 (CXCL12) initiates carcinoma derived MMP-9 secretion in the tumor microenvironment." (PMID 25734659, 2015). "The expression levels of BIRC5, TK1, TNNT1 and MMP9 were found to be positively related to tumor recurrence after cystic resection." (PMID 25970782, 2015). "Tumor samples of 417 patients were stained by immunohistochemistry, and the expression of MMP-9 in tumor cells was evaluated, using the median immunohistochemical score of 10 (range, 0-300) as the cut-off." (PMID 25888323, 2015). "Another familiar DEG in oncology is MMP9, matrix metallopeptidase 9, which promotes the progression of diverse cancers by improving tumor growth, migration, invasion, metastasis and angiogenesis." (PMID 25970782, 2015). "These include cell motility, secretion of lysosomal proteinases cathepsins B and L, expression/secretion of MMP9, invasion, expression of integrin receptor αΙIbβ3, tumor cell adhesion to endothelium, and spreading on subendothelial matrix." (PMID 26037302, 2015). "The anti-metastatic potential of DW-F5 was further confirmed by the extensive reduction in the expression of MMP-9 in tumours harvested from mice treated with DW-F5 confirming the in vitro results." (PMID 26061820, 2015). "HMGB1 in turn activated TLR4 and elevated the pro-tumor factors IL-6 and miR-21, together with other important factors like MMP9 and miR-155, to induce carcinogenesis." (PMID 25923834, 2015). "We analyzed tumor invasive potential by performing western blot analysis on tumor tissue to determine the expression levels of vimentin, MMP-9 and both the pro-form and the proteolytically processed activated form of MMP-2." (PMID 26083629, 2015). "Cumulatively, our results demonstrate that these two C3f-derived peptides are reflective of MMP-9 expression in tumor cells and can potentially be used as measures of EphA2 treatment efficacy." (PMID 25788424, 2015). "MMP-9 secretion is an important parameter in the invasion process of metastasis and its evaluation would give key insights into invasive potential in tumor cells." (PMID 25774696, 2015). "MMP9 plays a central role inangiogenesis, stromal remodeling, and consequently metastasis of different tumor types." (PMID 26384300, 2015). "Previous studies have validated that MMP-9 degrades the principal components of the ECM, collagen types IV and V, and gelatin and, thus, is closely associated with tumor cell invasion and metastasis." (PMID 25621068, 2015).
tumor (continued). "Correlation between the MMP-9 expression levels and the clinicopathological parameters of tumors did not identify any significant difference, with the exception of the depth of tumor invasion." (PMID 25621068, 2015). "The production of MMP-2 and MMP-9 are considered by many publications as tumor markers, in which, they promote the development and progression of tumor cells, along with facilitating migration, invasion and metastasis." (PMID 26588686, 2015). "In tumours, MMP-9 expression has been attributed to infiltrating inflammatory cells, and is regulated by the NF-κB pathway." (PMID 26158863, 2015). "NGAL was originally purified from human neutrophils and contributes to tumor progression by promoting MMP-9 activity through the formation of a complex, MMP-9/NGAL." (PMID 26663949, 2015). "DeClereck and colleagues demonstrated that MMP-9 was involved in the recruitment of bone marrow-derived leukocytes into the tumor microenvironment." (PMID 26729169, 2015). "Among this family of members, MMP-2 and MMP-9 have been characterized as crucial factors contributing to angiogenesis and tumor invasion." (PMID 25563361, 2015). "The group with tumor MMP-9 expression had a higher proportion of patients with adenocarcinoma histology (40.2% vs. 61.5%; p = 0.001) and more advanced stage (p = 0.001)." (PMID 25888323, 2015). "Degradation of the ECM is an essential step in tumor invasion and metastasis, and the MMP-9 was able to degrade the ECM and promote tumor cell metastasis." (PMID 26652622, 2015). "Another study provided evidence that low levels of MMP-9, both in vivo and in vitro, allowed for increased tumor angiogenesis; the vascularization of tumor cells is essential for tumor growth." (PMID 25664615, 2015). "In all patients who experienced tumor relapse, the clearance of the urinary MMPs, particularly MMP-9/NGAL in Postop-1w urine, was accompanied by the reappearance of the urinary MMPs in Post-r urine samples." (PMID 26663949, 2015). "Among these, MMP-9 (gelatinase-B), a crucial factor in angiogenesis, plays a critical role in the progression of a variety of tumor types." (PMID 25888323, 2015). "In detail, tumor-associated macrophages (TAMs) isolated in NSCLC and kept in short-term culture expressed high levels of Cathepsin K, COX-2, MMP-9, PDGF-B, uPA, VEGF, and HGF." (PMID 26425658, 2015). "We therefore performed this study to assess the prognostic impact of tumor MMP-9 expression, as determined by IHC staining, in patients with operable NSCLC." (PMID 25888323, 2015). "Both VEGF-C- and MMP-9-positive staining were found in the cytoplasm of tumor cells, in which brown-yellow particles were dispersively located." (PMID 26656588, 2015). "We have also demonstrated that high levels of miR-942 in tumor MRCC cells upregulates both MMP-9 and VEGF to induce endothelial cell migration and resistance to sunitinib." (PMID 24475095, 2014). "Elevated expression of MMP9 by tumor-infiltrating inflammatory cells in a mouse pancreatic cancer model mediated the release of bioactive VEGF-A from its extracellular reservoir." (PMID 24634660, 2014). "Embelin inhibited the production of pro-angiogenic IL-8 and VEGF/VEGFR as well as invasiveness-promoting MMP-2 and MMP-9 thus blocking production of tumorigenic mediators in the microenvironment of the tumor." (PMID 24694877, 2014). "Specifically, IL-6 triggers tumour cells to produce matrix metalloproteinase (MMP)-9 that promotes tumour growth by initiating angiogenesis." (PMID 24957270, 2014). "Studies of matrix metalloproteases (MMPs) in invasive cancers have indicated that MMPs play an important role in the development of tumor metastases, among which MMP-2 and MMP-9 are particularly associated with distant dissemination of malignant tumors." (PMID 25496480, 2014). "While inhibition of PLD abrogated MMP9 secretion, addition of PA rescued norepinephrine-induced MMP9 secretion that is crucial for tumor metastasis and invasion." (PMID 24103483, 2014).
tumor (continued). "In the present study, wnt3a expression was significantly correlated with MMP-9 expression in the primary tumor, mesenchyme and metastatic site." (PMID 24564183, 2014). "Recent studies have found that it has anticancer activity with its mechanism of action to inhibit the activity of MMP-2 and MMP-9 and thereby to inhibit the tumor growth, invasion, metastasis, and angiogenesis in cancer tissues." (PMID 24971318, 2014). "The tumor secretion of stem cell factor functions as a chemoattracting signal for mast cells; then mast cells produce angiogenic factors and MMPs (MMP-2 and MMP-9) to promote tumor vascularization." (PMID 24578639, 2014). "Tumours, unable to grow in gelatinase B/MMP-9 knockout mice, grow readily following auto-transplantiation of normal mouse bone marrow by a mechanism independent of endothelial cell progenitors but involving CD11b positive myelomonocytic cells." (PMID 24473089, 2014). "Our current study observed that both Enbrel and low-dose TNF-α pretreatments before IR markedly reduced the mRNA expressions of tumor promoting factors, IL-6 MMP-9 and E-selectin in IR liver." (PMID 24397824, 2014). "MMP-2 promotes cleavage of ECM proteins and is intensively expressed by tumour and stromal components of cancer, while MMP-9 modulates permeability of vascular endothelium." (PMID 24912879, 2014). "Higher MMP-9 mRNA expression was also detected in tumor specimens compared with matched epithelial tissues and lymph nodes (P<0.05)." (PMID 24845596, 2014). "MMP-2 and -9 can cleave latency-associated peptide to activate tissue growth factor β1, MMP-2 and MMP-9 have been shown to be critical for the “angiogenic switch in tumor angiogenesis." (PMID 25233229, 2014). "It is well understood that MMP-9 overexpression is a key factor in degradation of the extracellular matrix, an essential step in tumor invasion and metastasis; this role has been observed in human tissue and cell line studies of CRC." (PMID 24564183, 2014). "A very recent Gulo−/− study showed that physiological ascorbate supplementation dramatically reduced tumor metastases and necrosis, features that were associated with MMP-9 (a HIF-1 target gene) expression and tumor invasiveness." (PMID 25540771, 2014). "Certain myeloid immune suppressor cells have been found to promote tumor angiogenesis by the production of matrix metalloproteinase 9 (MMP-9)." (PMID 24877061, 2014). "eHsp90 has also been reported to regulate MMP-9 activity and tumor invasion as a component of an extracellular complex with the hyaluronan receptor CD44." (PMID 24805867, 2014). "Gelatinase B/MMP-9, however, also exhibits anti-tumor activity and plays important physiological functions." (PMID 24473089, 2014). "The MMP-9 plasma levels decreased from 125.6 ng/mL in the tumor control group to 43.1 ng/mL and 32.8 ng/mL in the CAPE and CAPPE–fed groups, respectively." (PMID 24960186, 2014). "These diverse cells produce a wide variety of inflammatory cytokines, chemokines, reactive oxygen species and secreted proteases (such as MMP-9), which in autocrine and paracrine manners control tumor progression." (PMID 24713998, 2014). "As an example, MMP9 was overexpressed 152-fold, which is pertinent since MMPs are involved primarily in the breakdown of extracellular matrix and possibly promotion of tumor invasion." (PMID 24716831, 2014). "Interaction between tumour cells and stroma at the invasive edge regulates gelatinase B/MMP-9 expression, which combined with gelatinase B/MMP-9 released by tumour-associated neutrophils and macrophages, increases invasiveness." (PMID 24473089, 2014). "In these tumors, well-known markers of tumor progression able to modulate tumor invasion and metastatic potential, such as Mmp2 and Mmp9, were consistently up-regulated." (PMID 24928374, 2014).